MIF (macrophage migration inhibitory factor)
Diseases named in the same sentence as MIF in open-access papers (continued):
Sharing a sentence is not in itself a finding about the gene and the disease.
depression (27 papers, 2010 to 2025). "Many investigations have identified MIF expression in the brain in significant areas associated with the behavioral symptoms of depression." (PMID 40333139, 2025). "MIF is also associated with major depressive disorder, and people with LongC have significant increases in depression and anxiety." (PMID 38612641, 2024). "The genetic deletion of MIF caused anxiety- and depression-like behavior and impairments in hippocampal-dependent memory in mice." (PMID 37513925, 2023). "In contrast, concerning depression severity, we even found an association of high MIF mRNA levels with low HAM-D scores at inclusion, but only in male MDD patients." (PMID 36555097, 2022). "Several reports suggest that MIF is implicated in depression, but its exact biological contribution to the disease is under debate." (PMID 26338025, 2015). "To further understand the role of MIF in depression, we studied depressive-like behaviour in congenic male and female MIF KO mice and wild-type (WT) littermates and the associated neurobiological mechanisms underlying the behavioural outcome." (PMID 26338025, 2015). "However, there are many aspects to be investigated concerning the association between MIF and depression, and future studies should work to clarify the relationship between central and peripheral MIF in depression." (PMID 40333139, 2025). "However, another study showed that the MIF -173C allele is a susceptibility factor for depression in type 2 diabetes patients." (PMID 38476376, 2024). "Thus, the effect of MIF genotype on the risk of depression and its possible sex-specificity and underlying mechanisms require further studies to potentially identify females at risk." (PMID 36555097, 2022). "Levels of macrophage migration inhibitory factor, neopterin, and tumor necrosis factor alpha were determined by enzyme-linked immunosorbent assay; response and remission were measured by reduction of the Montgomery Åsberg Depression Rating Scale score." (PMID 34646168, 2021). "Macrophage migration inhibitory factor (MIF) is an important multifunctional cytokine that is synthesized by several cell types in the brain and is expressed in brain areas associated with the behavioural symptoms of depression." (PMID 26338025, 2015). "Moreover, immunoinflammatory disorders such as major depressive disorder characterized by high levels of inflammatory biomarkers have been shown reduced MIF levels after antidepressants, suggesting the pathogenic role of MIF in the induction and maintenance of these disorders." (PMID 35628263, 2022). "CD74 is additionally the primary target receptor for macrophage migration inhibitory factor (MIF), a pro-inflammatory cytokine that is responsible for mediating the inflammatory effects in alcohol use disorders, depression, and neurodegenerative diseases." (PMID 38025429, 2023). "Network construction of overlapping arketamine, suicide, and depression genes identified macrophage migration inhibitory factor (MIF) as a central node." (PMID 37513925, 2023). "Macrophage migration inhibitory factor (MIF) is a controversially discussed inflammatory marker in major depressive disorder (MDD)." (PMID 36555097, 2022). "Clinical studies have found that serum levels of MIF are increased in depressed patients and correlate positively with depressive symptoms as measured with the Beck Depression Inventory short form." (PMID 26338025, 2015). "A link between MIF and depression has already been suggested but its exact role is still under debate." (PMID 26338025, 2015). "It has also been shown that MIF can increase the cytokine levels of TNF-α, IL-1β and IL-6 which have all been associated with depression." (PMID 26338025, 2015). "Despite significant evidence for MIF involvement in the pathobiology of depression, some uncertainty remains about its exact role." (PMID 24447830, 2014). "Future studies should work to elucidate the relationship between central and peripheral MIF in depression, if any exists." (PMID 24447830, 2014).
depression (continued). "It seems counterintuitive to assert that MIF is both an antidepressant and a biomarker of depression." (PMID 24447830, 2014). "With mounting evidence for a role for cytokines in depression, macrophage migration inhibitory factor (MIF) has emerged as a strong candidate for a pathophysiological role." (PMID 24447830, 2014). "Increased serum MIF was also observed after an immune challenge in pregnant patients with depressive symptoms as measured by the Center for Epidemiologic Studies Depression Scale (CES-D)." (PMID 24447830, 2014). "Conversely, increased serum MIF has been identified in both patients with major depression and healthy subjects with depressive symptoms, although these studies have shown mixed results." (PMID 24447830, 2014). "A study of male undergraduate students presented with a public speaking task determined that subjects with mild to moderate depression on the BDI demonstrated higher baseline serum levels of MIF as well as increased lymphocytes." (PMID 24447830, 2014). "Further work should also be done to clarify MIF’s role as a pro- or antidepressant and its place in the pathobiology of depression." (PMID 24447830, 2014). "Although there is much to be done, it seems beyond doubt that MIF has great potential in studies of the mechanisms of major depression." (PMID 24447830, 2014). "Inflammation and cytokines have emerged as a promising new avenue in depression research, and, in particular, macrophage migration inhibitory factor (MIF) has been shown to be significant in depression physiology." (PMID 24447830, 2014). "Research concerning MIF in relation to depressive disorders has similarly led to inconsistent observations." (PMID 23675319, 2013). "Further research is needed to clarify whether MIF acts as a pro-depressant or antidepressant and to define its role in the pathobiology of depression." (PMID 40333139, 2025). "A multilevel study of MIF in severe Depression (MDD) patients revealed that after three weeks of treatment, patients had significantly lower levels of MIF, but there was no strong evidence to support the utility of MIF as a biomarker for the diagnosis or monitoring of MDD." (PMID 40644836, 2025). "This project is the first to investigate three biological levels of MIF in depression." (PMID 36555097, 2022). "Depression and other neuropsychological disorders may also be aggravated by malfunctioning of the MIF due to synthesis of free radicals and nitric oxide (NO) causing further harm of neuronal integrity and viability." (PMID 36217471, 2022). "Taken together, there are heterogeneous data with respect to MIF’s role in depression." (PMID 36555097, 2022). "MIF is not only effective in ameliorating behavioral effects of stress in rodents but also in humans, where this compound has shown its effectiveness in alleviating the symptoms of major depression and bipolar disorder." (PMID 28945761, 2017). "Furthermore, the MIF can be released into the systemic circulation where it induces cardiocirculatory depression." (PMID 26318747, 2015). "The exact role for MIF in depression is therefore still controversial." (PMID 26338025, 2015). "Furthermore, patients suffering from major depressive disorder (MDD) had elevated levels of MIF compared to healthy controls." (PMID 26338025, 2015). "MIF levels in plasma may be incidental to the mechanisms of depression or may arise as a consequence of a different but related process." (PMID 24447830, 2014). "Imaging studies have emerged as an important modality in neuropsychiatric disorders, including depression; it may prove interesting to test how alterations in MIF expression affect the presentation of the disease on imaging studies." (PMID 24447830, 2014). "There are multiple lines of research pointing to a role for MIF in the pathobiology of depression." (PMID 24447830, 2014). "In this review we summarize current research on MIF and depression." (PMID 24447830, 2014).
depression (continued). "There is still much uncertainty about MIF’s exact pathophysiologic role, and whether its activity promotes or obstructs pathological processes in depression." (PMID 24447830, 2014). "MIF has also been examined as a biomarker in the context of clinical depression." (PMID 24447830, 2014). "If MIF is found to promote depression, then MIF inhibitors could be investigated as antidepressants; ISO-1, the most tested MIF inhibitor, has already been shown to cross the blood brain barrier." (PMID 24447830, 2014). "There are clear gaps in the research concerning MIF and depression." (PMID 24447830, 2014). "This could indicate (i) a shift towards an anti-inflammatory/inflammatory cytokine profile, contrary to what is typically observed in healthy third-trimester pregnancies, and (ii) lower levels of MIF, in contrast to findings in pregnant women with depressive disorders during the third trimester." (PMID 40333139, 2025). "Despite these data implicating MIF in the pathophysiology of MDD, the effects of ketamine on MIF levels, both in clinical studies and in animal models of depression, have not been explored, deserving future studies." (PMID 37513925, 2023). "Similar to the protein data, we could also not find any significant association of these relative MIF mRNA changes with the absolute change of any of the depression scales (all p > 0.3)." (PMID 36555097, 2022). "Moreover, MIF is modulated by glucocorticoids, and high, antiinflammatory doses of glucocorticoids inhibit MIF secretion; however, during pathological conditions characterized by glucocorticoid resistance, such as depression, it is conceivable that levels of MIF are increased." (PMID 27207917, 2016). "Thus, our results suggest that MIF has a role in promoting depressive-like behaviours in rodents, and further stresses the importance of examination of sex differences in animal models of depression." (PMID 26338025, 2015). "When this occurs, MIF’s role in depression - whatever it may be - will be highly relevant." (PMID 24447830, 2014). "Out of our 26-analyte panel, only three proteins (ApoH, ApoA1 and B2M) were altered in bipolar disorder patients and four (MIF, ACE, TNC and ILra) were changed in patients with depression." (PMID 26171982, 2015). "For example, the emerging role of macrophage migration inhibitory factors (MIF) in depressive disorder should not be omitted." (PMID 37834806, 2023). "A correlation of baseline or endpoint MIF values with depression severity or course was not examined." (PMID 36555097, 2022). "If MIF acts as an antidepressant, then anti-MIF therapeutics can be engineered not to cross the blood brain barrier, bypassing depression as a possible off-target effect." (PMID 24447830, 2014). "It is also possible that the two results are not mutually exclusive, and increased MIF in depressed individuals is a physiological adaptation to the pathobiological changes of depression." (PMID 24447830, 2014). "Like MIF, there is reason to believe that EPO could serve in a therapeutic capacity in the treatment of depressive disorders." (PMID 23675319, 2013). "As alluded to earlier, MIF and EPO might be related to depressive disorders, although the available data are admittedly limited." (PMID 23675319, 2013). "The authors observed that women previously diagnosed with major depressive disorder or bipolar had higher MIF responses than those women with no psychiatric disorder, suggesting a dysregulation of inflammatory responses during depression." (PMID 20150988, 2010). "However, in patients without prior medication, baseline MIF mRNA values correlated positively with depression severity at follow-up assessed by the HAM-D scale (rho = 0.311, p = 0.017)." (PMID 36555097, 2022). "It thus seems that although the findings concerning MIF in blood are not congruent with the potential involvement of this factor in depressive disorders, a better case exists for central involvement of MIF in depression." (PMID 23675319, 2013).
depression (continued). "Notably, the group with both depressive disorder and chronic T. gondii infection exhibited a distinct cytokine profile characterized by significantly elevated TNF, IL-6, and IL-10 levels and significantly reduced IL-8 and MIF levels compared to the other groups." (PMID 40333139, 2025). "These growth factors, to varying degrees, have been related to depressive disorders, although in the case of VEGF, MIF, and EPO it does not seem as if they systematically vary in depressed patients." (PMID 23675319, 2013). "In general, TRD and drug-free patients had similarly increased levels of inflammation-related genes: this applied to both the genes that had been measured before in depression (IL1-beta, IL-6, TNF-alpha and MIF) and those never measured before (A2M, CRP, P2RX7, CCL2 and STAT1)." (PMID 32699209, 2020).
glomerulonephritis (27 papers, 2009 to 2026). A renal disorder characterized by damage in the glomeruli. "Urinary MIF has previously been reported to be increased, and associated with the severity of renal injury, in human glomerulonephritis and has also been suggested as a potential biomarker for acute kidney damage in acute pyelonephritis." (PMID 26858715, 2016). "This could be explained by the fact that the diseased kidney tissues express MIF at dramatic levels, which raises the serum levels of MIF, and consequently, due to the underlying glomerulonephritis, a urinary output impairment ensues, leading to higher excretion of MIF in the urine." (PMID 40968277, 2026). "Previous studies have shown that MIF is a proinflammatory mediator of the innate immune system, and increased urinary MIF was related to the severity of kidney injury in glomerulonephritis or pyelonephritis." (PMID 34540864, 2021). "In recent literature, MIF has already been associated with AKI in divergent clinical settings of septic shock, liver transplantation, glomerulonephritis, and renal allograft rejection." (PMID 32932965, 2020). "Experimental models of glomerulonephritis have shown an upregulation of renal mRNA MIF, leading to the overexpression of MIF." (PMID 33133605, 2020). "Small molecule MIF antagonists also resulted in reduced glomerulonephritis and interstitial inflammation, lower levels of CD74+ and CXCR4+ leukocyte recruitment and decreased circulating TNF-α." (PMID 30787934, 2019). "MIF expression is increased in progressive renal injury due to glomerulonephritis and renal transplant rejection." (PMID 29924850, 2018). "To date, there is no data on the influence of pharmaceutical immunosuppression on mRNA expression of MIF, but one study showed lowered urinary MIF protein secretion after immunosuppression in patients with glomerulonephritis." (PMID 29027966, 2017). "The upregulation of MIF correlated significantly with the concentration of urinary MIF in patients with glomerulonephritis, pyelonephritis and renal allograft rejection, while systemic MIF concentrations were not increased in these patients." (PMID 28813470, 2017). "Increased MIF expression was also observed in MRL/lpr mice, and MIF deficiency attenuates macrophage recruitment, glomerulonephritis, and lethality in MRL/lpr mice." (PMID 27313397, 2016). "Renal MIF expression was identified in normal kidneys and it is upregulated in patients with glomerulonephritis and renal allograft rejection." (PMID 26272322, 2015). "Renal MIF is a constitutive expression in normal kidneys and is upregulated in patients with glomerulonephritis and renal allograft rejection." (PMID 23319831, 2012). "In human glomerulonephritis, elevated concentrations of urinary MIF reflect the severity of renal injury and AKI." (PMID 23319831, 2012). "MIF is constitutively expressed in the kidney and is upregulated in chronic kidney disease, glomerulonephritis, and oxidative stress." (PMID 20100315, 2010). "It has been established that upregulation of renal MIF mRNA expression in the endothelium, glomerular, and tubular epithelial cells is closely related to macrophage accumulation and renal tissue lesions in experimental glomerulonephritis." (PMID 26858715, 2016). "MIF is a key molecule in macrophage migration and accumulation at sites of injury and is involved in many inflammatory reactions during fibrogenesis, such as glomerulonephritis and lupus nephritis." (PMID 27313397, 2016). "Furthermore, anti-MIF intervention in experimental glomerulonephritis has revealed a generalized downregulation of numerous pro-inflammatory cytokines, chemokines and MIF-dependent signaling intermediates." (PMID 26272322, 2015). "Furthermore, elevated levels of MIF in the urine have been found in individuals with the progressive form of glomerulonephritis and those experiencing renal allograft rejections." (PMID 23319831, 2012).
glomerulonephritis (continued). "Neutralizing anti-MIF antibodies, small molecules or endogenous inhibitors or MIF−/− mice have shown that MIF aggravates anti-GBM glomerulonephritis, experimental IgAN, and lupus nephritis." (PMID 26441987, 2015). "Mice with MIF deletion are protected from immune-mediated lupus nephritis and treatment with a neutralizing anti-MIF antibody ameliorates kidney injury in crescentic anti-GBM glomerulonephritis." (PMID 38534333, 2024). "This study assesses the influence of immunosuppressive treatment on serum and urine MIF in patients with proliferative (PGN) and non-proliferative (NPGN) glomerulonephritis, and evaluates the potential of MIF in predicting outcomes." (PMID 26272322, 2015). "More recently, the inhibitor of MIF/CD74 interactions RPS19 prevented the development of glomerular crescents, necrosis, inflammation, renal dysfunction, proteinuria, and the upregulation of MIF and CD74 in anti-GBM glomerulonephritis." (PMID 26441987, 2015). "The study did not confirm that MIF has any prognostic value in the course of non-proliferative primary glomerulonephritis." (PMID 26272322, 2015).